HIF1A (hypoxia inducible factor 1 subunit alpha)
Diseases named in the same sentence as HIF1A in open-access papers (continued):
Sharing a sentence is not in itself a finding about the gene and the disease.
tumor (continued). "Oppositely, maintenance of HIF-1α expression seems to correlate to tumour cells de-differentiation and normal cells primitiveness." (PMID 19587783, 2009). "HIF-1α is highly expressed in various tumor tissues and plays an important role in regulating hypoxia, and tumor invasion and progress." (PMID 19245702, 2009). "Division according to percentage of perimembranous or diffuse staining pattern turned out to be more important than intensity and/or percentage of positive tumor cytoplasm in relation to HIF-1α or clinicopathologic parameters." (PMID 19302703, 2009). "Staining for nuclear HIF-1α in the tumor cells was significantly decreased in mice treated with 2ME2 compared to vehicle-treated mice, confirming that the 2ME2 treatment was effective in vivo." (PMID 19727403, 2009). "In the present study, we further show a molecular mechanism involving miR-20b regulating HIF-1α and VEGF and being regulated by HIF-1α, through which tumor cells adapt to different oxygen concentrations." (PMID 19893619, 2009). "When stratified by BRCA mutation status, HIF-1α positivity was significantly correlated with BRCA1 (23/32, 72%) compared with BRCA2 (12/32, 38%) and BRCAX (20/49, 41%) associated tumours (P=0.008)." (PMID 19724277, 2009). "Immunohistochemicaly VEGF-A, VEGF-C, HIF-1α and Ki67 were detected on tumor cells and the staining was performed on tissue microarrays (TMA)." (PMID 19302703, 2009). "The increased ROS in response to hypoxia can promote cancer cell survival and tumor growth through activating hypoxia inducible factor 1α (HIF-1α)." (PMID 19497135, 2009). "The patterns of HIF-1α expression in tumor tissues, when present, were mixed nuclear/cytoplasmic and HIF-1α was positive in 54.93%(39/71) of the patients." (PMID 20003271, 2009). "Immunohistochemical expression of HIF-1α was observed in the cytoplasm and in the nucleus of the tumor cells in all investigated cases but with different staining intensity." (PMID 18983642, 2008). "The adaptational response of tumour cells against hypoxia is thought to be mainly mediated by HIF-1α, which transactivates a number of target genes leading to metabolic adaptation, angiogenesis, invasion/metastasis and apoptosis resistance." (PMID 18854835, 2008). "In 28 of these cases (74%) an intensive nuclear HIF-1α expression of surrounding tumor cells was observed (Figure 4B1,2 and 4C1,2)." (PMID 18983642, 2008). "Nakai by using Western Blotting concluded that in 52 patients with sub-optimally resected stage III/IV tumours and further treated with combination postoperative chemotherapy Taxol, Carbo (TC), HIF-1α expression correlated with significantly better survival." (PMID 19014607, 2008). "In previous in vitro experiments we demonstrated the relevance of tumor differentiation for HIF-1α inducibility." (PMID 18983642, 2008). "Our data also indicate that increasing HIF-1α expression performs an important function in tumor invasiveness and correlation with the TNM stage." (PMID 18452596, 2008). "The overall survival of patients with tumours that stained strongly for HIF-1α was significantly shorter than that of patients with tumours that stained weakly or were negative for HIF-1α (p = 0.01)." (PMID 19014607, 2008). "In renal cancer, loss-of-function mutations of VHL can cause HIF1α stabilisation, thereby inducing VEGF and PDGF overexpression and sustained tumour angiogenesis." (PMID 18797463, 2008). "In these cases HIF-1α activation was seen in viable cohesive tumor epithelia surrounding necrosis and in dissociated tumor cells, which subsequently die." (PMID 18983642, 2008). "Immunopositivity for nuclear HIF-1α was present in all adenocarcinomas but was heterogeneous within tumours." (PMID 18648372, 2008).
tumor (continued). "Carbonic anhydrase 9 (CA9), such as hypoxia-inducible factor 1α (HIF-1α), is known to be a marker of hypoxia, but its role in a hypoxic tumour microenvironment is still unclear." (PMID 18841153, 2008). "This was also reflected in Western blot results for HIF-1α expression analysis in tumor tissues, which were markedly reduced in the ENMD-1198 treated tumors." (PMID 18651980, 2008). "The combined effect of tumour HIF-1α and HIF-2α expression was analysed in relation to patient outcome." (PMID 18283323, 2008). "In these samples nuclear HIF-1α expression was detected in cohesive tumor epithelia surrounding necrosis and in dissociated cells destined to undergo cell death (Figure 4A1,2)." (PMID 18983642, 2008). "Both factors are in principle very important in supporting tumour growth as HIF-1α controls angiogenesis and adenosine exerts a profound immunosuppressive activity, thus protecting the tumour from inflammatory cells." (PMID 18612415, 2008). "In our study, 88% of all CC-RCC showed activation of HIF1-α throughout the whole tumour section, independently of the presence of necrosis." (PMID 17505508, 2007). "HIF-1α regulates cellular responses to physiological and pathological hypoxia, and studies demonstrate that HIF-1α is a potential target for tumor angiogenesis." (PMID 19936090, 2007). "In our study, two predominant types of HIF-1α expression were observed: staining of the tumour's invasive edge and focally positive staining." (PMID 17179985, 2007). "HIF-1α is an oxygen-dependent transcriptional activator, which plays crucial roles in the tumor angiogenesis." (PMID 19936090, 2007). "The use of HIF-1α as an indicator of tumor response to EGFR-targeted therapy should be further investigated in preclinical studies and in the clinical setting." (PMID 17931419, 2007). "When tumor cells are exposed to a hypoxic environment, HIF-1α is activated to promote the transcription of glucose transporters and glycolytic enzymes." (PMID 17623095, 2007). "Tumour cells in perinecrotic regions of ductal carcinoma in situ lesions, where HIF-1α levels are high, exhibit a more aggressive phenotype, with loss of differentiation and downregulation of oestrogen-receptor (ER) expression." (PMID 18096060, 2007). "Detroit 562 tumours expressed more HIF-1α at baseline, and also had a higher degree of increase over time with tumour growth, as seen by the 400 vs 200% increases over 7 days in Detroit 562 vs HEP2 tumours." (PMID 17342092, 2007). "As FIH-1 is able to modulate HIF-1α activity, it would be expected to affect tumour behaviour in a similar manner." (PMID 18096060, 2007). "Agents targeting FIH-1 would therefore further complement the repertoire of therapeutic agents aimed at inhibiting HIF-1α activity in tumours." (PMID 18096060, 2007). "On the other hand, the tumour-suppressor function of pVHL remains intact despite the presence of the corresponding HIF-1α mutant." (PMID 17211469, 2007). "In contrast, overexpression of HIF-1α was found to retard the growth of similar RCC-derived experimental tumours." (PMID 17387348, 2007). "HIF-1α is stabilised and strongly detected by Western blot in nuclear protein extracts from cells cultured at 2% O2 compared to normoxic controls in both tumour cell lines." (PMID 16832411, 2006). "HIF-1α is a "master" gene controlling the hypoxic response in mammalian cells and thus plays an important role in tumor growth." (PMID 16438736, 2006). "Following stimulation by hypoxia or its mimetic agent, CoCl2, the tumour cells showed significant nuclear localisation of HIF-1α." (PMID 17156434, 2006). "In this xenograft model, tumours were exposed to chronic, or diffusion-limited, hypoxia, which HIF-1α reflects poorly." (PMID 16404365, 2006).
tumor (continued). "In this study, we demonstrated that modulating the expression level of HIF-1α was able to increase or decrease apoptosis of a tumor cell line, A549, under hypoxic stress." (PMID 16438736, 2006). "Whereas Panc-1, the more aggressive undifferentiated cell line, showed a modest increase of NDRG1 mRNA or protein under different HIF-1α stabilizer, compared to the prominent response of the moderately differentiated tumour cell line, Capan-1." (PMID 16832411, 2006). "The product of the von Hippel Lindau (vHL) tumour suppressor gene targets HIF-1α for oxygen-dependent proteolysis, acting as the substrate recognition component of an E3 ubiquitin ligase." (PMID 17156434, 2006). "The widespread occurrence of upregulated HIF-1α in common cancers and the involvement of hypoxia pathways in tumor angiogenesis certainly argue for its importance and wide applicability." (PMID 17166265, 2006). "Hypoxia-inducible transcription factor-1α (HIF-1α), which plays an important role in controlling the hypoxia-induced glycolysis pathway, is a "master" gene in the tissue hypoxia response during tumor development." (PMID 16438736, 2006). "A trend to a correlation between DEC-1 and CA9 (P=0.05) and between DEC-1 and Hif-1α expression (P=0.05) was found in primary tumours." (PMID 16251878, 2005). "The expression of HIF-1α turned out to be of prognostic relevance in different tumours reviewed by Semenza." (PMID 16035955, 2005). "Tumour biopsy analysis for microvessel density, endothelial cell apoptosis and nuclear localisation of HIF-1α as a marker of tumour hypoxia also suggested that endostatin was having an in vivo biological effect on human cancer." (PMID 16234821, 2005). "Tumour HIF-1α nuclear expression was significantly correlated with that of CA9 membranous expression and low MVD." (PMID 15558070, 2005). "In multivariate Cox analysis we compared the overall survival and the disease free survival according to clinical usual prognostic factors tumour size and nodal status and also to cyclin D1 and Ki 67 with the HIF-1α expression." (PMID 16035955, 2005). "Detectable levels of HIF-1α (HIF-1α ≥ 1%) were found within the tumour cells in 63,5% (54/85) of the oral SCCs." (PMID 16035955, 2005). "HIF-1α nuclear expression was significantly higher in carcinomas than in tumours of uncertain behaviour and in benign tumours." (PMID 15558070, 2005). "Tumour hypoxia and VHL gene mutations in RCC lead to accumulation of HIF-1α, this protein then leads to transcription of a number of genes which predominantly affect angiogenesis and assist in tumour expansion." (PMID 16222313, 2005). "Expressions of CA9 and Hif-1α were correlated in primary tumours (P<0.001) and in lymph node metastases (P=0.005)." (PMID 16251878, 2005). "The prognostic relevance of HIF-1α in tumours derived from squamous epithelium is however controversial." (PMID 16035955, 2005). "Nodal status, tumour size and HIF-1α expression were identified by Cox regression as independent predictors of overall survival." (PMID 16035955, 2005). "CA9 expression is consistent with the upregulation of HIF-1α nuclear expression in poorly differentiated tumours, recalling the situation observed in most carcinomas studied so far." (PMID 15558070, 2005). "It has also been revealed that EGFR and HER-2 can potentiate tumour cell adhesion to endothelial cells, by enhancing the synthesis of hypoxia-inducible factor (HIF)-1α, and/or carbonic anhydrase-9 through a PI3 kinase-dependent pathway." (PMID 14710236, 2004). "The percentage of high HIF-1α expression cases increased with tumour stage according to pTNM system." (PMID 12966423, 2003). "In addition, the key gene P4HA2 in the hypoxia signature has been demonstrated to be involved in the regulation of malignant phenotypes of tumor cells and the regulation of HIF-1α stability." (PMID 41559646, 2026). "In general, as a response to hypoxia, HIF-1α upregulation facilitates tumor survival." (PMID 41438587, 2026).
tumor (continued). "Targeting HIF-1α will lower tumor vascularization by decreasing VEGF production." (PMID 41614951, 2026). "Specifically, many compounds inhibit pathological tumor angiogenesis (via VEGF/HIF-1α/NF-κB/MMP-related signaling) while supporting endothelial defense and microvascular recovery in non-cancerous tissues through antioxidant, anti-inflammatory, and anti-apoptotic pathways (e.g., Nrf2/HO-1)." (PMID 41948735, 2026). "Consequently, HILRNA68 can increase HIF-1α transcriptional activity, creating a positive feedback loop that greatly increases tumor cell invasion and proliferation." (PMID 41614928, 2026). "miR-21′s upregulation contributes to treatment resistance via its inhibition of tumor suppressors such as PTEN and its downstream activation of AKT/ERK signaling and HIF-1α–mediated angiogenesis, mechanisms implicated in promoting invasive and aggressive tumor behavior." (PMID 41511367, 2026). "In vivo, GEM inhibited tumor growth and downregulated HIF1A, UBR5, and FGFR1." (PMID 42318009, 2026). "For example, mild hypoxia in periphery region of large tumor tissue promotes HIF-1α." (PMID 41438587, 2026). "Furthermore, H. pylori-induced immune responses and the hypoxic conditions within the tumor niche activate HIF-1α, which collaborates with BRD4 to upregulate glycolysis-related genes such as Slc2a1 (Solute Carrier Family 2 Member 1) and Hk2 (hexokinase 2)." (PMID 41171531, 2026). "However, in a hypoxic tumor microenvironment, HIF-1α degradation slows down due to decreased hydroxylation by PHD2 in the absence or lack of oxygen." (PMID 41614951, 2026). "Targeting HIF-1α/VEGF mediated tumor angiogenesis can inhibit tumor progression." (PMID 41438587, 2026). "Moreover, mRNA expression levels of proliferation‐associated genes, including HIF‐1α target genes, were higher in HFD‐fed mice compared to CD‐fed mice, indicating accelerated tumor growth in the HFD group." (PMID 41160815, 2026). "Once activated, HIF‐1α enhances the secretion of CCL2 from the tumor." (PMID 41160815, 2026). "Tumor hypoxia detection and imaging become possible through the utilization of three separate techniques: oxygen‐sensitive nanoprobes, hypoxia‐responsive MRI contrast agents and HIF‐1α‐targeted nanoprobes." (PMID 41521160, 2026). "HIF-1α plays a critical role in tumor growth, metastasis, and immune evasion." (PMID 41710663, 2026). "However, tumor cells can develop resistance mechanisms through metabolic reprogramming via hypoxia-inducible factor-1α (HIF-1α) and the nuclear factor E2-related factor 2 (Nrf2)-driven reductive pathway, which partially limits the drug's clinical efficacy." (PMID 42072452, 2026). "In addition, prolonged hypoxia can lead to therapeutic resistance (i.e., sorafenib treatment) can further induce the HIF-1α and NF-κB signalling, promoting a more aggressive and treatment resistant tumour behaviour." (PMID 41476776, 2026). "18F-FDG uptake is closely associated with several key tumor processes, including glucose metabolism (mediated by GLUT1 and hexokinase I), hypoxia response (via HIF-1α), angiogenesis (driven by VEGF and CD34), and the PI3K/Akt/mTOR signaling pathway, which promotes tumor invasiveness." (PMID 40699302, 2026). "HIF-1α/GPER signaling further triggers the expression of vascular endothelial growth factor (VEGF) in CAFs to enhance tumor angiogenesis and progression, and both HIF-1α and GPER are indispensable for VEGF-induced human vascular endothelial cell tube formation." (PMID 41141392, 2026). "In the mKRAS G12C group, 90.6% of cases exhibited HIF-1α positivity in the tumor microenvironment." (PMID 39996842, 2025). "ID may stabilize HIF-1α in specific tumor microenvironments, enhancing tumor angiogenesis and invasiveness." (PMID 41190142, 2025). "Hypoxia-inducible factor-1α (HIF-1α) is a crucial transcription factor with a wide array of target genes, including nearly 100 genes related to hypoxia adaptation, inflammation development, and tumor growth." (PMID 40887582, 2025).
tumor (continued). "In normoxic conditions, HIF-1α is subject to proteasomal degradation; however, in a hypoxic tumor microenvironment, it becomes stabilized and translocate to the nucleus, where it activates genes associated with angiogenesis, glycolysis, and epithelial-to-mesenchymal transition (EMT)." (PMID 40136686, 2025). "Interestingly, excessive availability of the tumor-derived oncometabolite D-2-hydroxyglutarate destabilizes HIF-1α and boosts OXPHOS in Treg cells, thereby promoting their accumulation in tumors." (PMID 40468052, 2025). "Furthermore, activated AKT can elevate HIF-1α protein levels via mTOR, enhancing anaerobic glycolysis in tumor cells and thereby promoting tumor growth." (PMID 41463642, 2025). "Consequently, RUNX2 and HIF-1α synergistically promote angiogenesis, a vital process in the tumour microenvironment that provides nutrients and oxygen to the growing tumour." (PMID 40806771, 2025). "In addition, tumor cells showed scattered immunoreactivity for the α subunit of hypoxia-inducible factor (HIF-1α)." (PMID 40213016, 2025). "This may be especially important in the context of the tumor microenvironment as this may regulate cell–cell signaling driven by HIF1α and HIF2α that, in general, favor mechanisms that bolster tumor growth and metastasis." (PMID 41614767, 2025). "In the tumor microenvironment, angiogenesis is a key factor for tumor growth and metastasis, and PLZF may indirectly affect tumor angiogenesis by regulating the HIF-1α/VEGF signaling pathway." (PMID 40601668, 2025). "Notably, Beclin-1 expression showed a positive correlation with hypoxia-inducible factor 1-alpha (HIF-1α), a hypoxia-inducible transcription factor known to promote tumour aggressiveness." (PMID 40805271, 2025). "Additionally, recent studies demonstrated that activation of the VHL/HIF-1α/VEGF pathway relates with tumor cell occurrence, growth, prognosis, and drug resistance." (PMID 41030787, 2025). "Since HIF1α expression has been shown to interfere with NK cell function, the role of HIF1α in NK cells was investigated in relation to the ability to infiltrate tumor spheroids." (PMID 40736709, 2025). "Under hypoxic conditions, HIF-1α overexpression amplifies adenosine biosynthesis and signaling through A2A receptors, establishing an immunosuppressive microenvironment that promotes tumor progression and drug resistance." (PMID 40791591, 2025). "We hypothesize that JFAD’s anti-tumor effects may partly result from its regulation of succinate levels, affecting HIF-1α and SUCNR1 signaling pathways." (PMID 41568043, 2025). "One feature observed in hypoxic conditions, as found in the microenvironment of aggressive tumors, was the binding of the transcription factor to hypoxia-inducible factor (HIF)-1α in the nucleus, and this heterodimeric complex induced oncogenic processes in order to promote tumor growth." (PMID 41295250, 2025). "Given that PRCC‐TFE3 upregulates HIF1α and HIF2α to regulate hypoxia‐related signatures in vivo, we next investigated whether Hif1α and/or Hif2α are essential for tumor development." (PMID 39807625, 2025). "Hypoxia changes mediated by HIF-1α and elevated ROS levels enhance the differentiation, recruitment, survival, and immunosuppressive functions of MDSCs, fostering a tumor-supportive microenvironment that promotes cancer progression, immune evasion, and therapy resistance." (PMID 39857427, 2025). "Consequently, the hypoxic tumor microenvironment promoted SKA3 upregulation through HIF-1α-mediated transcriptional activation." (PMID 41298345, 2025). "For instance, under hypoxic conditions, tumor cells may activate hypoxia-inducible factor (HIF-1α) to regulate antigen expression, thereby impacting the recognition capability of immune cells." (PMID 40270890, 2025). "Also, in cancer cells, we predict that higher TSGA10 expression suppresses glycolysis (via HIF-1α inhibition), aligning with reduced tumor aggressiveness." (PMID 40507237, 2025).